SLC7A11 (solute carrier family 7 member 11)
Diseases named in the same sentence as SLC7A11 in open-access papers (continued):
Sharing a sentence is not in itself a finding about the gene and the disease.
pancreatic cancer (continued). "Gene ontology analysis of 43 different ferroptosis regulators revealed that both SLC7A11 and SLC3A2 are upregulated in pancreatic cancer samples and are associated with gemcitabine resistance." (PMID 35280777, 2022). "In summary, solasonine inhibits the TFAP2A/OTUB1 SLC7A11 axis to activate ferroptosis and suppress pancreatic cancer cell progression." (PMID 35494004, 2022). "Compared with normal pancreatic ductal cells, the expression of SLC7A11 was upregulated in most pancreatic cancer cell lines (p < 0.05)." (PMID 34938318, 2021). "We also validated SLC7A11 expression in multiple pancreatic cancer cell lines in vitro and found that it was upregulated in most pancreatic cancer cell lines (p < 0.05)." (PMID 34938318, 2021). "Studies have found that the solute carrier family 7 member 11 (SLC7A11) gene is overexpressed in pancreatic cancer cells, and the survival time of mice with SLC7A11 gene deletion induced by CRISPR-Cas9 is doubled compared with that of normal mice." (PMID 34503532, 2021). "A study using genetically engineered mice with SLC7A11 knockout revealed tumor-selective ferroptosis and inhibited the growth of pancreatic cancer." (PMID 34938318, 2021). "Besides, solasonine extracted from Solanum nigrum L. facilitates solute carrier family 7 member 11 (SLC7A11) degradation to induce ferroptosis of pancreatic cancer cells." (PMID 40640922, 2025). "Moreover, it has been documented that both Cys and SLC7A11 are critical for pancreatic ductal adenocarcinoma growth, and Cys depletion induces the death of pancreatic tumor cells in mice." (PMID 40723225, 2025). "Although SLC7A11 has not been demonstrated to be directly associated with pancreatic fibrosis, research on its relationship with pancreatic tumors and inflammation has revealed promising new avenues for fibrosis studies." (PMID 40249927, 2025). "When SLC7A11 was downregulation or inactivation, genetically or pharmacologically, shown to potently induce lipid peroxidation and ferroptosis in pancreatic cancer cells, led to proliferation arrest and cell death, suggesting great potential as a strategy for anticancer therapy." (PMID 38017014, 2023). "Therefore, we deduced that LINC00578 impeded the ubiquitination of SLC7A11, which inhibits ferroptosis in pancreatic cancer." (PMID 36846713, 2023). "This study elucidated that LINC00578 acts as an oncogene to promote pancreatic cancer cell progression and suppress ferroptosis by directly combining with UBE2K to inhibit the ubiquitination of SLC7A11, which provides a promising option for the diagnosis and treatment of pancreatic cancer." (PMID 36846713, 2023). "Moreover, we showed that SLC7A11-positive macrophages were detected not only in kidney cancer but also in lung, colon, ovarian, and pancreatic cancer." (PMID 36470862, 2022). "MiR-139-5p/SLC7A11 restrains the progression of pancreatic cancer via PI3K/Akt pathway." (PMID 35465835, 2022). "SLC7A11 expression was found to be upregulated in many pancreatic cancer cell lines." (PMID 35280777, 2022). "SLC7A11 is the main functional subunit and inhibition of SLC7A11 expression can induce ferroptosis, which has been confirmed in vivo by SLC7A11 depletion leading to ferroptosis in pancreatic cancer." (PMID 36033459, 2022). "MiR-557 was also found to suppress pancreatic cancer cells through miR-557/SLC7A11/PI3K/AKT." (PMID 35087570, 2021). "Similarly, understanding the role of SLC7A11 in pancreatic cancer progression and its potential as a target for combination therapy could lead to novel treatment strategies." (PMID 40249927, 2025). "Furthermore, we mechanistically explored whether LINC00578 inhibits ferroptosis in pancreatic cancer cells by reducing ubiquitin-conjugating enzyme 2K- (UBE2K-) mediated SLC7A11 degradation." (PMID 36846713, 2023). "However, it is elusive whether LINC00578 participates in pancreatic cancer progression through SLC7A11-independent ferroptosis." (PMID 36846713, 2023).
pancreatic cancer (continued). "Therefore, SLC7A11 is one of the main negative regulators of ferroptosis and this has been recently confirmed by in vivo evidence of SLC7A11 depletion leading to ferroptosis in pancreatic cancer." (PMID 33499222, 2021). "In addition to cell proliferation, SLC7A11 (xCT) also participates in PCD in pancreatic cancer." (PMID 33783998, 2021). "Moreover, the expression of SLC7A11 is upregulated in the pancreatic tumor tissues and pancreatic cancer cells can increase SLC7A11 expression in response to oxidative stress, which results in the increase in GSH synthesis and enables tumor cells to survive in the presence of elevated ROS." (PMID 33117704, 2020). "We further performed qRT-PCR on five selected ferroptosis-related genes (HMOX1, CHAC1, SLC3A2, SLC7A11, and FTH1) in pancreatic cancer cells after 12 and 24 h of CBC treatment." (PMID 40790027, 2025). "In pancreatic cancer cells, METTL3 regulated ferroptosis and lipid peroxidation levels through SLC7A11." (PMID 40175350, 2025). "Through in vitro cell experiments, we clarified that Na-OHB downregulated CAV1 expression in pancreatic cancer cells, inhibiting the transcription of the CAV1/AMPK/NRF2 downstream ferroptosis-protective genes SLC7A11 and SLC40A1." (PMID 40180904, 2025). "Taken together, this study revealed that LINC00578 promoted pancreatic cancer progression and inhibited ferroptosis by directly binding UBE2K to suppress SLC7A11 ubiquitination." (PMID 36846713, 2023). "This study illustrates that LINC00578 promotes pancreatic cancer cell progression and suppresses ferroptosis by directly binding UBE2K to inhibit the ubiquitination of SLC7A11." (PMID 36846713, 2023). "Compared to normal tissues, mRNA levels of OTUB1, SLC7A11 and GPX4 were significantly upregulated in pancreatic cancer tissues." (PMID 35494004, 2022). "Knockout of solute carrier family 7 member 11 (SLC7A11) provided significant benefit in a mouse genetic model of pancreatic cancer, without inducing markers of other types of cell death beyond ferroptosis." (PMID 39473490, 2024). "In the second study, congenital epithelial-specific Slc7a11 KO did not alter the incidence, onset, and progression of pancreatic cancer." (PMID 37770957, 2023). "Importantly, we first demonstrated that LINC00578 overexpression can inhibit ferroptosis by targeting SLC7A11 in pancreatic cancer, suggesting that LINC00578 regulates pancreatic cancer progression by inhibiting SLC7A11-dependent ferroptosis." (PMID 36846713, 2023). "The cystine‐glutamate antiporter xCT protein SLC7a11 regulates cellular sensitivity to ferroptosis by regulating glutathione synthesis, and inhibition of SLC7a11 improves the efficacy of anti‐CTLA‐4 in the colon and pancreatic cancers." (PMID 37860928, 2023).
pancreatic cancer (continued). "The predictive powers of OTUB1, SLC7A11 and GPX4 in pancreatic cancer were highly accurate." (PMID 35494004, 2022). "To further confirm this finding, we knocked down the expression of SLC7A11 in vitro in Panc-1 cell and found SLC7A11 knockdown did not affect the proliferation of pancreatic cancer." (PMID 34938318, 2021). "Given Slc7a11 deletion is safe, and considering it does not compromise antitumor immune response in vivo, xCT inhibition is now posed as a promising therapeutic approach for pancreatic cancer." (PMID 35065965, 2022).
melanoma (58 papers, 2014 to 2026). A malignant, usually aggressive tumor composed of atypical, neoplastic melanocytes. "In melanoma, BRAF inhibitors can sensitize melanoma cells to agents that cause ferroptosis, which reduces the abundance of SLC7A11 transcripts." (PMID 38336727, 2024). "Accordingly, trametinib or vemurafenib decrease the expression of SLC7A11 in melanoma cells bearing BRAFV600E mutation." (PMID 37795022, 2023). "Loss of SLC7A11 in melanoma abrogated tumour metastasis in several in vivo murine models of experimental and spontaneous metastasis." (PMID 35804831, 2022). "SLC7A11 expression is also involved in the invasion and metastasis of melanoma, and loss of SLC7A11 can inhibit melanoma metastasis in vivo." (PMID 36552652, 2022). "Meanwhile, SLC7A11 has been identified as a useful marker to predict the susceptibility of metastatic melanoma cells to ferroptosis." (PMID 36081847, 2022). "SLC7A11 overexpression is linked to enhanced tumor proliferation and progression in melanoma and poor overall survival and advanced pathology in papillary thyroid carcinoma." (PMID 35280777, 2022). "Deficiency of the FRG (SLC7A11) in mice with melanoma was more susceptible to anti‐PD‐L1 therapy, which suggests again the role of ferroptosis in anti‐tumor immunity." (PMID 33969928, 2021). "As a classical multi-tyrosine kinase inhibitor, sorafenib promotes ferroptosis in melanoma cell by inhibiting SLC7A11 activity and depleting glutathione (GSH)." (PMID 40497999, 2025). "Three patients with advanced BRAF+MEK inhibitor-resistant melanoma, who suffered from progression upon dabrafenib plus trametinib therapy, were treated with vorinostat (360 mg/day, orally), which suppressed SLC7A11 in taken biopsies." (PMID 39935431, 2025). "Mechanistically, T-cell secreted IFN-γ inhibits the expression of solute carrier family 7 member 11 (SLC7A11) in melanoma cells, leading to reduced cell viability, which can be further potentiated by ferroptosis-inducing agents." (PMID 40108693, 2025). "Ferroptosis, characterized by lipid peroxidation, can overcome melanoma resistance by targeting the solute carrier family 7 member 11 (SLC7A11)/glutathione peroxidase 4 (GPX4) axis." (PMID 40497999, 2025). "Downregulation of SLC7A11 has been proposed as a marker of induction of ferroptosis in melanoma metastatic cells." (PMID 37996827, 2023). "Another study reported ferroptosis inducers (FINs) such as sorafenib, RSL3, sulfasalazine, and erastin, synergistically increased the effect of radiotherapy in various cancers, including melanoma, by reducing SLC7A11 expression or inhibiting GPX4." (PMID 37996827, 2023). "It has been reported that inhibiting SLC7A11 activity, increases the efficacy of ferroptosis-promoting drugs in melanoma cells." (PMID 37996827, 2023). "SLC7A11 expression has been shown to be elevated in cancers such as melanoma, both before and after acquired drug resistance." (PMID 35326683, 2022). "The negative association between CD8+ T cell infiltration, IFN-γ expression, and the expression of SLC3A2 and SLC7A11 was also shown in human melanoma tissues." (PMID 35795206, 2022). "In human melanoma tissues, both SLC7A11 and LC3A2 are negatively correlated with the number of CD8+ T cells, the expression level of IFN-γ and patient outcome." (PMID 35847022, 2022). "Together, these studies highlight the potential for targeting SLC7A11 in combination with other therapies to counteract the altered redox homeostasis present in melanomas both before and after acquired drug resistance." (PMID 35326683, 2022).
melanoma (continued). "SLC7A11 has also been shown to be upregulated in BRAF inhibitor-resistant melanoma cell lines, which themselves exhibited elevated oxidative stress as compared to drug naive cells." (PMID 35326683, 2022). "Vorinostat, an histone deacetylase inhibitor (HDACi), enhances the levels of ROS in both MAPKi-sensitive and resistant melanoma cells by suppressing the expression of the Solute Carrier Family 7 Member 11 (SLC7A11) gene, encoding xCT." (PMID 32528879, 2020). "Microarray analyses on two human melanoma cell lines revealed that riluzole stimulates expression of the cystine-glutamate amino acid antiporter, xCT (SLC7A11)." (PMID 30425240, 2018). "Additionally, the impact of Slc7a11 and Nqo1 knockdown on the cytotoxicity of leukoderma-inducing phenols was examined in B16-4A5 melanoma cells." (PMID 39858507, 2025). "Treatment of resistant melanoma cells with the pan-HDAC inhibitor vorinostat downregulated SLC7A11 (the gene of the cysteine-glutamate antiporter xCT), which further increased intracellular ROS levels to a cytotoxic level specifically in the drug-resistant cells, triggering apoptosis." (PMID 39935431, 2025). "Therefore, SLC7A11/GSH/GPX4 is an essential axis in melanoma ferroptosis." (PMID 37373523, 2023). "Transcriptional networks further enforce ferroptosis resistance in melanoma: EZH2 copy number amplification silences KLF14, upregulating SLC7A11 to enhance glutathione synthesis, while APOE reduces polyunsaturated fatty acids and upregulates GPX4." (PMID 41170386, 2025). "GNA triggered ferroptosis in melanoma cells by decreasing lncRNA nuclear-enriched abundant transcript 1 (NEAT1) and downregulating levels of SLC7A11/glutathione peroxidase 4 (GPX4)." (PMID 40900835, 2025). "6-MF targets PTBP1 to inhibit circPIAS1 biogenesis and reduce circPIAS1-108aa.6-MF inhibits PI3K-AKT pathway; combined with IFN-γ, it enhances STAT1 phosphorylation, inhibits SLC7A11/GPX4 pathway, promoting melanoma ferroptosis." (PMID 41347180, 2025). "When combined with IFN-γ, it significantly enhances STAT1 phosphorylation levels and inhibits the SLC7A11/GPX4 axis, thereby promoting ferroptosis in melanoma cells." (PMID 41347180, 2025). "The combination of 6-MF and immunotherapy reduced melanoma proliferative capacity, increased intracellular oxidative stress, and promoted, phosphorylation to inhibit the SLC7A11/GPX4 signaling pathway and promote ferroptosis in melanoma cells." (PMID 41347180, 2025). "While lnc NEAT1 is known to be upregulated in melanoma, downregulation of lnc NEAT1 induces ferroptosis through weakening of the direct binding to SLC7A11, indirectly resulting in inhibiting GPX4 and inducing ferroptosis." (PMID 37795022, 2023). "Both of these systems are dependent on the amino acid cysteine, which is imported through the cystine/glutamate antiporter xCT (system xc−) comprised in part by the NRF2 transcriptional target, SLC7A11, which also has upregulated expression in melanomas." (PMID 35326683, 2022). "In a melanoma mouse model, knockout of ferroptosis suppressor ACSL3/SLC7A11 or using cyst(e)inase was found to significantly enhance the anticancer effect of radiotherapy (8 Gy, single fraction) by promoting tumor lipid oxidation and ferroptosis." (PMID 35847022, 2022). "The relevance of glutamine transport in melanoma is supported by data indicating that SLC1A5 and SLC7A11 are overexpressed in melanoma cells when compared to melanocytes." (PMID 31461993, 2019). "The protein levels of SLC7A11 and GPX4 were downregulated by 6-MF, IFN-γ or their combination in A375 and B16-F10 melanoma cells, indicating that ferroptosis might be induced in the presence of these therapeutic strategies." (PMID 41347180, 2025).
melanoma (continued). "In our experiments, we found that HPF was able to reduce SLC7A11 expression in A375 and FO-1 melanoma cells, but not in the SK-Mel-28 cell line." (PMID 37507910, 2023). "Immunohistochemical results suggested SLC7A11 and FANCD2 staining in melanoma." (PMID 35309947, 2022). "Consistent with other reports in melanoma cells, it was recently shown that BRAFi-resistant melanoma exhibits a strong activation of Nrf2, leading to the activation of PPP, which is involved in the regeneration of GSH and SLC7A11 expression." (PMID 33091721, 2020).